BAP1 (BRCA1 associated deubiquitinase 1)
Description:
Deubiquitinating enzyme that plays a key role in chromatin by mediating deubiquitination of histone H2A and HCFC1. Catalytic component of the polycomb repressive deubiquitinase (PR-DUB) complex, a complex that specifically mediates deubiquitination of histone H2A monoubiquitinated at 'Lys-120' (H2AK119ub1). Does not deubiquitinate monoubiquitinated histone H2B. The PR-DUB complex is an epigenetic regulator of gene expression and acts as a transcriptional coactivator, affecting genes involved in development, cell communication, signaling, cell proliferation and cell viability. Antagonizes PRC1 mediated H2AK119ub1 monoubiquitination. As part of the PR-DUB complex, associates with chromatin enriched in histone marks H3K4me1, H3K4me3, and H3K27Ac, but not in H3K27me3. Recruited to specific gene-regulatory regions by YY1. Acts as a regulator of cell growth by mediating deubiquitination of HCFC1 N-terminal and C-terminal chains, with some specificity toward 'Lys-48'-linked polyubiquitin chains compared to 'Lys-63'-linked polyubiquitin chains. Deubiquitination of HCFC1 does not lead to increase stability of HCFC1. Interferes with the BRCA1 and BARD1 heterodimer activity by inhibiting their ability to mediate ubiquitination and autoubiquitination. It however does not mediate deubiquitination of BRCA1 and BARD1. Able to mediate autodeubiquitination via intramolecular interactions to counteract monoubiquitination at the nuclear localization signal (NLS), thereby protecting it from cytoplasmic sequestration. Negatively regulates epithelial-mesenchymal transition (EMT) of trophoblast stem cells during placental development by regulating genes involved in epithelial cell integrity, cell adhesion and cytoskeletal organization.
Synonyms: KIAA0272; hucep-6; UCHL2; HUCEP-13; KURIS; TPDS1; UBM2; UVM2
Tractability: PROTAC: UniProt records ubiquitination sites on it; ubiquitination databases record sites on it; its protein half-life has been measured; a small molecule that binds it is known.
Target class: Enzyme
Chemical probes: ML078
Gene: Protein-coding gene on chromosome 3 (52,401,008 to 52,410,008, reverse strand). Ensembl gene ENSG00000163930.
Subcellular location: Cytoplasm; Nucleus; Chromosome
Subcellular location (Human Protein Atlas): Nucleoplasm; Cytosol
Pathways (Reactome):
DNA Repair: Recruitment and ATM-mediated phosphorylation of repair and signaling proteins at DNA double strand breaks
Metabolism of proteins: UCH proteinases
Gene Ontology:
Molecular function: chromatin binding; cysteine-type deubiquitinase activity; histone H2A deubiquitinase activity; protein binding; peptidase activity; chromatin DNA binding
Biological process: monoubiquitinated protein deubiquitination; negative regulation of DNA-templated transcription; positive regulation of establishment of protein localization to mitochondrion; protein deubiquitination; protein K48-linked deubiquitination; regulation of cell cycle; regulation of cell growth; heterochromatin formation; negative regulation of cell population proliferation; protein modification process; cell population proliferation; common myeloid progenitor cell proliferation; erythrocyte differentiation; erythrocyte maturation; gene expression; granulocyte differentiation; hematopoietic stem cell homeostasis; in utero embryonic development; leukocyte proliferation; mitotic cell cycle; myeloid cell apoptotic process; neutrophil differentiation; nucleate erythrocyte differentiation; platelet morphogenesis; regulation of gene expression; and 4 more
Cellular component: chromosome; cytoplasm; cytosol; nucleoplasm; nucleus; PR-DUB complex
Genetic constraint (gnomAD): Loss-of-function variants: 16 observed, 74.95 expected, observed/expected ratio (o/e) 0.21, 90% interval 0.14 to 0.32. The upper end of that interval is the gene's LOEUF score, 0.32, which puts it in group 1 of 6, group 1 being the genes least tolerant of losing a copy. Missense variants: 699 observed, 979.9 expected, observed/expected ratio (o/e) 0.71, 90% interval 0.67 to 0.76. Synonymous variants: 362 observed, 393.48 expected, observed/expected ratio (o/e) 0.92, 90% interval 0.84 to 1.
Gene-disease validity (ClinGen):
ClinGen rates the evidence that BAP1 causes each of these diseases.
BAP1-related tumor predisposition syndrome (autosomal dominant): Definitive. BAP1-related tumor predisposition syndrome (TPDS) is an inherited cancer-predisposing syndrome, associated with germline mutations in BAP1 tumor suppressor gene.
Cancer hallmarks: invasion and metastasis (promotes); change of cellular energetics (promotes); escaping programmed cell death (suppresses); proliferative signalling (promotes); genome instability and mutations (suppresses)
Homologues: Orthologues: chimpanzee BAP1 (99% identical), macaque BAP1 (99% identical), guinea pig BAP1 (95% identical), pig BAP1 (95% identical), rat Bap1 (94% identical), mouse Bap1 (93% identical), rabbit BAP1 (91% identical), dog BAP1 (80% identical), tropical clawed frog bap1 (71% identical), zebrafish bap1 (68% identical), Drosophila melanogaster caly (30% identical), Caenorhabditis elegans ubh-2 (7% identical), and 2 more. Paralogues in human: UCHL5 (20% identical), UCHL3 (8% identical), UCHL1 (8% identical).
Diseases named in the same sentence as BAP1 in open-access papers:
BAP1 is named in the same sentence as 286 diseases in open-access papers, as found by Europe PMC text mining. Sharing a sentence is not in itself a finding about the gene and the disease. The quoted sentences say what the papers report.
mesothelioma (316 papers, 2011 to 2026). A usually malignant and aggressive neoplasm of the mesothelium which is often associated with exposure to asbestos. "A decrease in nuclear HIF-1α signal was observed in mesothelioma cases with germline BAP1 mutations, particularly those with biallelic mutations, which revealed BAP1’s interaction with HIF-1α." (PMID 41602827, 2026). "This study showed for the first time that BAP1 mutations are associated with a novel hereditary cancer syndrome that predisposes to mesothelioma, uveal melanoma, and clear cell renal cell carcinoma, among other cancers." (PMID 40361508, 2025). "Approximately 35% of germline BAP1 mutation carriers develop mesothelioma, typically asbestos‐independent, early‐onset, and slow‐progressing, with nuclear BAP1 loss and papillary features." (PMID 40904706, 2025). "BAP1 mutation is an early event in mesothelioma pathogenesis, and it is one of the most frequently mutated genes in MPM, more often in PEM than PSM, and in MIS." (PMID 39941848, 2025). "Recently, BAP1 tumour predisposition syndrome (BAP1‐TPDS), a hereditary cancer syndrome caused by germline BAP1 mutations, has been recognised as another cause of mesothelioma." (PMID 40979255, 2025). "Rucaparib is another PARP inhibitor studied in a phase II trial for treatment refractory BAP1 deficient or BRCA-1 mutated mesothelioma." (PMID 41375064, 2025). "In mesothelioma, BAP1 inactivation is associated with alterations in the polycomb repressive complex 2 (PRC2) pathway, which regulates histone methylation, a key process in gene expression control." (PMID 40362535, 2025). "In BRCA1-associated protein 1 (BAP1) wild-type mesothelioma, ADAR2 up-regulation enhanced the A-to-I editing of transcripts and 3ʹ-UTR." (PMID 39126156, 2025). "BAP1 has been linked to a specific mesothelioma subtype with distinct clinical and histopathological features, often associated with a relatively better prognosis compared to other PM subtypes." (PMID 40016284, 2025). "Although germline BAP1 heterozygous mutations are known to predispose to human mesothelioma, the findings presented here indicate that germline Bap1 mutations do not result in a statistically significant risk of mesothelioma in mice." (PMID 40867321, 2025). "MiST is an open-label parallel-arm phase 2 trial which explored the efficacy of rucaparib, a PARP inhibitor, in patients with PM with BAP1-deficient or BRCA1-deficient mesothelioma pretreated with chemotherapy." (PMID 40361508, 2025). "The incidence rate of mesotheliomas in human BAP1-mutation carriers is much higher than the rate of spontaneous mesotheliomas in mice carrying heterozygous Bap1 germline mutations." (PMID 40867321, 2025). "Meso-29, a patient with a likely pathogenic BAP1 germline splice variant, had a family history of mesothelioma." (PMID 40174508, 2025). "This was previously reported as a germline mutation in two individuals with mesothelioma and cutaneous melanoma, who were suspected to have BAP‐1 tumor predisposition syndrome." (PMID 39492623, 2025). "BAP1 is a tumor suppressor that is frequently mutated in deadly cancers, including UM, ccRCC, cholangiocarcinoma and mesothelioma." (PMID 40754831, 2025). "A comparative analysis for survival using data from SEER identified 23 mesotheliomas with germline BAP1 mutations, including peritoneal and pleural mesothelioma." (PMID 40361508, 2025). "In a preclinical model, mesothelioma cell lines with BAP1 protein loss were sensitive to inhibition of FGFR." (PMID 40361508, 2025). "While germline mutations in BAP1 are rare, they markedly increase the risk of developing mesothelioma and other cancers." (PMID 40362535, 2025).
mesothelioma (continued). "In 2016, we reported spontaneous mesotheliomas in 2 of 93 FVB/N mice with different germline Bap1 heterozygous mutations compared to 0 of 43 WT littermates that had been sacrificed at the time of publication." (PMID 40867321, 2025). "In PM, BAP1 as tumor suppressor contributes to mesothelioma development, and loss of BAP1 leads to uncontrolled cell growth." (PMID 40361508, 2025). "Regarding the prognosis, germline BAP1 mutations predispose carriers to developing mesothelioma; however, these same mutations render mesotheliomas less aggressive and possibly more sensitive to chemotherapy." (PMID 40361508, 2025). "BAP1-loss mesothelioma often has low arginine expression, making it more likely to respond to arginine deiminase (ADI-PEG20)." (PMID 40361508, 2025). "Several preclinical studies showed increased sensitivity to EZH2 inhibition in BAP1-deficient models compared to wild-type mesothelioma." (PMID 40361508, 2025). "In the context of mesothelioma, the role of BRCA1-associated protein 1 (BAP1) as both a diagnostic and prognostic marker is well established." (PMID 40559230, 2025). "It has been described that 30% of carriers of germline BAP1 mutations have developed mesothelioma, underscoring the key role of BAP1 preventing the malignant transformation of mesothelial cells." (PMID 40361508, 2025). "The relations between BAP1 loss and PD-L1 expression in mesothelioma was explored in clinical trials." (PMID 40361508, 2025). "A notable case involves mutations in the tumor suppressor gene BAP1, which have been linked with increased susceptibility to mesothelioma following asbestos exposure." (PMID 39891174, 2025). "This disruption suggests that mesotheliomas with BAP1 mutations are sensitive to inhibitors targeting EZH2, a component of the PRC2 complex." (PMID 40362535, 2025). "Somatic and germline mutations in the BAP1 gene are prevalent in mesothelioma, uveal melanoma, and clear cell renal cell carcinoma." (PMID 40000790, 2025). "In many cohorts, approximately 60–70% of sporadic mesotheliomas exhibit nuclear loss of BAP1, consistent with biallelic inactivation." (PMID 41375066, 2025). "BAP1 is involved in epigenetic deregulation, and the loss of BAP1 in mesothelioma alters histone modification patterns, altering gene expression." (PMID 40361508, 2025). "Overall, in our data from all genetic backgrounds (FVB/N, 129/Sv, C57BL/6), 2 of 329 mice with a germline Bap1 heterozygous mutation developed mesothelioma, compared to 0 of 227 WT mice." (PMID 40867321, 2025). "Researchers started a phase II trial to evaluate the impact of tazemetostat, an EZH2 inhibitor, in relapsed PM patients with inactivated BAP1 since mesothelioma cells with inactivated BAP1 are susceptible to EZH2 pharmacologic inhibition." (PMID 40227645, 2025). "One male patient with BAP1 germline mutation died of complications of mesothelioma at the age of 69 years, 42 months after the diagnosis of one BIMT." (PMID 39268598, 2025). "These probabilities provide evidence suggesting an increased risk of mesothelioma in Bap1-mutant mice compared to WT mice." (PMID 40867321, 2025). "BAP1 PTVs have been associated with a range of cancers, including cutaneous and uveal melanoma, kidney cancer, mesothelioma, and basal cell carcinoma." (PMID 40073867, 2025). "Germline Bap1 heterozygous mice are at increased risk of developing mesothelioma upon asbestos exposure, even to minimal amounts, which is the leading environmental factor associated with the risk of this aggressive malignancy." (PMID 40867321, 2025). "A phase II trial evaluated the PARP inhibitor niraparib in patients with solid tumors, including mesothelioma, harboring a BAP1 mutation or other DDR genes." (PMID 40361508, 2025).
mesothelioma (continued). "Several studies have identified germline BAP1 mutations in families with a high incidence of mesothelioma, suggesting a hereditary predisposition to the disease." (PMID 40361508, 2025). "Among these, BAP1-deficient mesotheliomas have drawn particular attention due to the pleiotropic regulatory functions of this gene, which range from DNA damage repair and cell cycle control to chromatin remodeling." (PMID 41463268, 2025). "Mesothelioma is one of the cancers linked to pathogenic germline variants of BAP1; indeed, germline mutations in BAP1 are responsible for 1–7% of malignant mesotheliomas." (PMID 40227645, 2025). "Studies by several groups have documented that most mesothelioma patients carrying a germline mutation of BAP1 or other cancer-predisposing genes have been exposed to asbestos." (PMID 40867321, 2025). "These in vivo results thus show the therapeutic potential of the proposed combination for BAP1-deficient mesothelioma." (PMID 38519707, 2024). "The immune cell composition in BNC closely resembles that in human mesothelioma with BAP1, NF2, and CDKN2A loss—M2 macrophages, T cells, and B cells make up a significant proportion of the leukocyte population." (PMID 38879686, 2024). "By combined targeting we were able to demonstrate a significant antitumor effect in both in vitro and in vivo settings, indicating a potentially promising new treatment modality for BAP1-deficient mesothelioma." (PMID 38054839, 2024). "A phase 2 trial including 74 patients with BAP1 deficient mesothelioma treated patients with PeM with the EZH2 inhibitor tazemetostat as a monotherapy." (PMID 38642130, 2024). "We demonstrated the efficacy of the combination of ATM and EZH2 inhibition against BAP1-deficient mesothelioma in preclinical models, indicating the potential of this combination as a novel treatment modality using BAP1 as a biomarker." (PMID 38519707, 2024). "Overall, germline BAP1 mutations are very rare in consecutive series of mesothelioma patients, although approximately 6% of patients with a family history of mesothelioma and other cancers carry a pathogenic mutation." (PMID 38673021, 2024). "In summary, we demonstrate that the simultaneous inhibition of EZH2 and ATM is a highly synergistic regimen against preclinical models of BAP1-deficient mesothelioma." (PMID 38519707, 2024). "Mice with germline Bap1 heterozygous mutations have enhanced susceptibility to mesothelioma upon minimal exposure to crocidolite or chrysotile asbestos." (PMID 38784478, 2024). "As the immunohistochemical profile was inconclusive for mesothelial proliferation, except for BAP1 loss, the diagnosis of mesothelioma was established mainly based on their transcriptomic profile." (PMID 39059063, 2024). "Mutations in the BAP1 gene, observed in a significant proportion of mesotheliomas, play a crucial role in suppressing cell death mechanisms." (PMID 39030439, 2024). "Collectively, our data shows that the combinatorial strategy of EZH2i and ATMi is a highly efficacious treatment against BAP1-deficient mesothelioma in vitro." (PMID 38519707, 2024). "It has previously been established that inhibition of EZH2 is therapeutically effective in BAP1-deficient mesothelioma in preclinical settings." (PMID 38054839, 2024). "They concluded that sensitivity to asbestos is increased in mesothelioma patients with pathogenic germline mutations in BAP1 or other DNA repair genes." (PMID 38784478, 2024). "Detection of the BAP1 mutation as a loss of BAP1 protein expression made an important contribution to the differentiation of mesothelioma from benign mesothelial hyperplasia." (PMID 38280040, 2024). "Recently, the interest for HDACi in mesothelioma management and other BAP1 mutated cancers, such as uveal melanoma, greatly increased, as demonstrated by several studies." (PMID 39204360, 2024). "To assess the potential clinical value of our finding, we tested a BAP1-deficient and a BAP1-proficient human mesothelioma cell line." (PMID 38054839, 2024).